VEGFA (vascular endothelial growth factor A)
Diseases named in the same sentence as VEGFA in open-access papers (continued):
Sharing a sentence is not in itself a finding about the gene and the disease.
tumor (continued). "Recent evidence also supports the potential of exosomal miR-26a-5p released by EC tumor cells and uptaken by lymphatic endothelial cells to induce lymphatic vessel generation and promote lymphatic spread of EC via LEF1/c-Myc/VEGFA axis." (PMID 39188680, 2024). "Significant upregulation of PTGS2, VEGFA, KDR, CXCR1, and CXCR2 expression were observed in tumour samples compared with paired normal samples." (PMID 38426619, 2024). "Vascular endothelial growth factor A (VEGF-A) and its receptor VEGFR2 represent major tumor angiogenic mechanisms." (PMID 38200582, 2024). "VEGFA, in turn, activates the AKT1 pathway, creating a self-reinforcing loop that promotes tumor growth and angiogenesis." (PMID 38666020, 2024). "Previous research has highlighted lncRNA’s participation in multiple signalling pathways, such as Wnt/β-catenin, TGF-β/Smad, STAT3 and VEGFA/VEGFR2, consequently influencing tumour invasion and metastasis, tumour angiogenesis." (PMID 39267831, 2024). "To analyze the synergistic roles of PHF5A and VEGFA proteins in ESCC cell progression, we firstly overexpressed PHF5A to reconfirm the tumor promotion of PHF5A in ESCC." (PMID 38429756, 2024). "VEGFA is a member of VEGF family, which is critical in tumor angiogenesis, the division and proliferation of vascular endothelial cells and lymphatic endothelial cells in tumor tissues." (PMID 39935706, 2024). "Our results suggest that the production of MC4 is due to the presence of many ILB+ macrophages at the tumor-normal interface, which secrete IL-1β that acts on ADRB2 on VEGFA+ MCs." (PMID 39840068, 2024). "Specifically, endothelial cells exhibited a notable increase in angiogenic genes, including “Angiogenesis” and “VEGFA-VEGFR2 signaling”, suggesting active vascular remodeling to accommodate tumor growth." (PMID 39468431, 2024). "Our study provides new insights into the oncogenic roles of ID4 in tumor cell migration and YAP/TAZ pathway activation, suggesting VEGFA/ VEGFR2/ integrin β3 axis as a potential target for BC treatment." (PMID 38321003, 2024). "In our study, we found that PTGS2 and VEGF signalling pathway genes (VEGFA, VEGFB, KDR, CXCR1 and CXCR2) were upregulated in OSCC tumour tissues compared to their paired normal tissues." (PMID 38426619, 2024). "Induced by the hypoxic conditions of tumors, Vascular Endothelial Growth Factor A (VEGF-A) is the primary angiogenic factor responsible for the development of tumor vessels and is essential for tumor growth." (PMID 39337337, 2024). "NRP-1 also acts as a co-receptor, enhancing the attachment of the vascular endothelial growth factor A (VEGF-A) to the VEGF receptor, a signaling pathway important in tumor angiogenesis." (PMID 39594723, 2024). "Immunohistochemistry was employed to assess the expression levels of COX‐2, CD31, VEGFA, MMP2, and MMP9 in tumor tissues in order to investigate the antioxidant properties of garlic peel extract, specifically its ability to suppress COX‐2 expression." (PMID 39554336, 2024). "While numerous studies have explored the expression levels of different molecules in tumor tissues, the current study aims to investigate the expression pattern of certain proteins (ILK, EphA2, and VEGFA) in a sample of LNs from CRC." (PMID 39525153, 2024). "Among genes that are more highly expressed in TAN, the vascular endothelial growth factor A (VEGFA), which was reported to enhance the permeability of vascular endothelial cells and promotes tumor metastasis, stands out." (PMID 37931958, 2024). "M6A modification mediated by METTL3 is essential for the activation of tumor progression and angiogenesis mediated by TEK/VEGFA." (PMID 39295872, 2024). "Studies have found that co-administration of anti-VEGFA antibody in vivo promotes the persistence of CAR T cells and tumor control." (PMID 38687357, 2024). "It is therefore worth noting that anti-inflammatory chemokines including CSF1, CD276, VEGFA, and CX3CL1 were upregulated in pedB tumor epithelial cells." (PMID 39482394, 2024).
tumor (continued). "The objective of this study was to evaluate the expression of VEGFA and KDR proteins in cRCC and their correlation with neo-angiogenesis and postoperative tumor relapse." (PMID 39000466, 2024). "This molecule influences the activity of VEGFA, ERBB, mTOR, TGF-β, and the PTEN/PI3K/AKT pathway, thereby affecting the process of tumor angiogenesis." (PMID 39001478, 2024). "Ensuing research has illuminated that Tumor Endothelial Cells (TEC) contribute to the constitution of tumor immune tolerance under hypoxic conditions, and can engage with CAF through VEGFA." (PMID 39075485, 2024). "Studies suggest that FB can secrete various factors, including VEGFA, PDGFC, FGF2, and osteopontin, which are known to stimulate angiogenesis in tumor tissues." (PMID 39759522, 2024). "HIF-1α, VEGFA, and VEGFC have been reported to act as factors that contribute to tumour angiogenesis." (PMID 38035445, 2024). "In tumor angiogenesis, the vascular endothelial growth factor (VEGF) and its receptors are considered the most crucial factors, and VEGFA occupies the leading role." (PMID 39596828, 2024). "miR-17-92 exerts its inhibitory effect on the progression of CRC by reducing tumor angiogenesis which is achieved by targeting several tumor angiogenesis-inducing genes, including TGFBR2, HIF1α, and VEGFA, both in vivo and in vitro." (PMID 38534736, 2024). "Although most FDA-approved anti-angiogenic drugs for cancer treatment are VEGFA/VEGFR2 inhibitors, these inhibitors can lead to development of resistances or increased tumour aggressiveness in patients." (PMID 38256941, 2024). "In the context of ICIs, these drugs are thought to act primarily on T cells, stimulating them to secrete IFN-γ, which in turn reduces endothelial VEGFA and increases the levels of CXCL-9, CXCL-10, and CXCL-11, contributing to tumor vascular normalization." (PMID 39850892, 2024). "Increased expression of vascular endothelial growth factor-A (VEGF-A) and hypoxia-inducible factor-1α (HIF-1α), a tissue inhibitor of metalloproteinases-1 (TIMP-1), was observed in tumorous samples compared to adjacent normal tissues." (PMID 39062015, 2024). "Through comprehensive analysis using GEPIA, TCGA, CancerMiRNome, and dbDEMC databases, we investigated the expression of miR‐378a‐3p, VEGFA, and RGC‐32 in PC tissues and adjacent tissues, exploring their probability as tumor markers." (PMID 39606802, 2024). "By preventing the connection between ARNT and TACC3, which in turn prevents VEGFA production and secretion and ultimately inhibits angiogenesis, CORO1C-47aa adversely affects tumour angiogenesis." (PMID 38622617, 2024). "A TAM population, F4/80+ macrophages, transformed from Kupffer cells, localized around vessels in tumours and expressed key angiogenic markers, including VEGFA, TIE2, and CD34, signifying its essential role in tumour vascularization." (PMID 38303024, 2024). "Necroptosis was found to enhance VEGFA expression through the activation of the JAK2-STAT3 pathway, promoting tumor proliferative and invasive capabilities in CC." (PMID 39247606, 2024). "RAB11B-AS1, a long noncoding RNA (lncRNA), enhances VEGFA and angiopoietin-like 4 (ANGPTL4) expression in hypoxic BC cells in a HIF-2α-dependent manner, promoting tumor angiogenesis and metastasis." (PMID 38799423, 2024). "Results showed that the regulatory factors CRNDE, EDN1, JUNB, and MAP2K1/2, ZFP36 mainly regulate differentially expressed genes (VEGFA, EGFR, PLAUR) to regulate invasion of cells, invasion of tumor, and microtubule dynamics." (PMID 38711992, 2024). "Co-treatment with lenvatinib and CQ resulted in a more pronounced reduction in VEGFA levels in the K1 and BCPAP cell supernatants, and xenograft tumor models confirmed these findings, indicative of the cytoprotective nature of lenvatinib-induced autophagy." (PMID 39272847, 2024).
tumor (continued). "We stained tissue sections of the tumor-normal interface from 15 ccRCC patients for CD68, IL-1b, VEGFA and tryptase and analyzed the proximity of each MC4 cell to the nearest IL-1β+ macrophage and other macrophages." (PMID 39840068, 2024). "As mRNA expression does not necessary corresponds to protein expression, next immunohistochemistry was applied to detect the occurrence and cellular localization of VEGFA and KDR in tumor tissues." (PMID 39000466, 2024). "Tumor angiogenesis, driven by vascular endothelial growth factor-A (VEGF-A), plays a pivotal role in tumor growth and progression." (PMID 38678209, 2024). "The gene LGALS4 exhibited the highest expression in tumor cells, while the gene VEGFA from the MAPS signature was highly expressed in various cell types, including myeloid cells and tumor cells." (PMID 38555418, 2024). "While TCM from untreated BC cells induced increased expression of VEGFR2, VEGFA, FGFR1, HIF-1α and PDGFRB, this effect was significantly inhibited by the muscone administration to tumor cells prior to isolation of the 231TCM and 549TCM." (PMID 38898449, 2024). "IFN-γ enhances the motility of antigen-specific CD8+T cells towards their target antigens and downregulates the expression of vascular endothelial growth factor A (VEGFA), leading to decreased blood flow within tumor tissues." (PMID 39030523, 2024). "Emerging studies have proposed that hypoxia-induced miR-210 facilitates tumour angiogenesis and cellular permeability in PDAC, negatively regulating EFNA3 expression and participating in the PI3K/AKT/VEGFA or Wnt/β-catenin/RHOA pathways." (PMID 38341827, 2024). "EPHA2 and VEGFA activate both PI3K/AKT and the extracellular signal-regulated kinase 1/2 (ERK1/2) signaling pathways to induce tumor progression by increasing tumor cell proliferation and vasculogenic mimicry." (PMID 38503745, 2024). "Immunohistochemical results also revealed decreased expression of Ki67, a tumor proliferation marker, and the HIF1a, GLUT1, and VEGFA proteins in OE_IDH1 H22 xenografts." (PMID 38622131, 2024). "Based on the results obtained, PTGS2, VEGFA, KDR, CXCR1 and CXCR2 were found to be significantly overexpressed in tumour samples compared to paired normal samples." (PMID 38426619, 2024). "We next proved that in vitro co-culture of the ex vivo F4/80+TAMs with the endothelial cells (SVEC4–10) under tumor-cell conditioned media (TCM) greatly stimulated the expression of a few key angiogenic markers including CD31, CD34, TIE2, VEGFA, Ki67, etc.." (PMID 36781833, 2023). "VEGFA and PGF showed distinct positive correlations with hypoxia scores in most cancers, indicating a potential correlation with tumor aggressiveness." (PMID 37852616, 2023). "The decrease of VEGFA, TGFβ1 and EGFR upon anti-PD-L1 treatment in PD-L1 low tumor cells provides a rationale for the use of those antibodies in PD-L1 low tumors." (PMID 38152616, 2023). "In the clinical group Tumor status: Tumor free and with tumor, the genes TOP2A, BIRC5, VEGFA had highly statistical significance, while the genes HIF1A, ACSL3, FTH1 didn’t have statistical significance." (PMID 37248280, 2023). "Inter-tumor Core and Rim regions showed significantly higher relative expression of hypoxia response genes, including LDHA, VEGFA, LOX, PLAUR, SERPINE1, and IGFBP3." (PMID 37434262, 2023). "Surprisingly, the proportion of anti-tumour immune cells, growth factors and cytokines in BC patients in the low-ACI group was higher, while high-ACI patients had a higher expression of VEGFA." (PMID 37469408, 2023). "It is noteworthy that ATR-101 therapy also partially reversed the effects of tumor-cell conditioned medium on the expression of HIF1A, VEGFA, and CXCL8 in TAM-like cells, but M0 macrophages were unaffected." (PMID 37426676, 2023). "In melanoma, miR-155 derived from the tumor inhibits SOCS1 and promotes the activation of the JAK2/STAT3 signaling pathway, increasing FGF2, VEGFA, and MMP9 levels in CAFs." (PMID 37605155, 2023).
tumor (continued). "Three signaling pathways (STAT3/VEGFA, HIF1/VEGFA, and AKT) have been reported to regulate tumor angiogenesis." (PMID 36720310, 2023). "In tumor cells with ITGA5 knockdown, qRT‐PCR and Western Blotting revealed decreased expression of ANGPT1, ANGPT2, and VEGFA, when compared to control cells." (PMID 36999964, 2023). "Using the Kruskal–Walls test to compare data, we found that overexpression of VEGFA, CTNNB1, MMP7, and CD44 genes promoted primary tumor and cancer metastasis in CRC tissues." (PMID 36672201, 2023). "Looking at these results, it can be said that the decreased VEGFA, E-cadherin, TGFβ1 and EGFR expression in PD-L1 low tumor cells after treatment is specific to anti-PD-L1 MoAb treatment." (PMID 38152616, 2023). "The tumour tissues and adjacent normal tissues of patients with HCC from Hunan Provincial People's Hospital were collected to verify the expression of VEGFA by immunohistochemistry, immunofluorescence, Western blotting and qPCR." (PMID 36729917, 2023). "In our study, we found that VEGFA level was significantly decreased after LAMP2A knockdown and upregulated after LAMP2A overexpression in vitro, then we confirmed this result in tumor tissue." (PMID 36913368, 2023). "METTL21A plays a role in protein modification pathways, while ANG and VEGFA are essential for vascular endothelial cell function, with implications for conditions like ALS and tumor angiogenesis." (PMID 38681774, 2023). "Tumor cells‐secreted CXCL1 and CXCL8 recruit neutrophils and promote activation of ERK and JNK signaling pathways and expression of VEGFA and MMP9 in neutrophils, which induce tumor lymphangiogenesis and facilitate LN metastasis of tumor cells." (PMID 36670069, 2023). "Exposure of HCT116 tumor cells for 24 h to 64CuCl2 induced the upregulation of some hypoxia-responsive genes such as the HMOX1, MMP9, and VEGFA, the most striking overexpression being registered in the case of the HMOX1 gene." (PMID 37415761, 2023). "By releasing angiogenic factors including S100A8 and S100A9, as well as activating vascular endothelial growth factors A (VEGFA) in the extracellular matrix and MMP9, tumor angiogenesis was maintained by neutrophils." (PMID 36609243, 2023). "Thus, patients with KRAS- or NRAS-mutant tumours should be treated with a chemotherapy doublet (FOLFOX or FOLFIRI) or triplet (FOLFOXIRI) in combination with the anti-angiogenic antibody bevacizumab targeting the vascular endothelial growth factor A (VEGFA) in first line." (PMID 37466791, 2023). "Gene set enrichment analysis (GSEA) pathway analysis revealed that the complement system, WNT signaling, DNA replication, VEGFA-VEGFR2 signaling, and metabolic reprogramming were the top five ranked pathways in EPCAM(+) tumor epithelial cells of EOCC." (PMID 37964075, 2023). "Overall, T cell activation status of circulating and tumour-infiltrating T cells correlated with response to treatment and adverse tumour biology as well as levels of immunosuppressive and pro-angiogenic PIGF and VEGFA present within the TME." (PMID 35986757, 2023). "Previous studies have shown that tumor cells can release cytokines, such as CSF1, IL-34, and VEGFA, which can downregulate the glycolysis level of TAMs and induce polarization to M289." (PMID 37781517, 2023). "VEGFA/VEGFR also plays an important role in T cell exhaustion, especially in tumor-induced T cell exhaustion." (PMID 38001101, 2023). "In turn, iMSC secrete IL-6, LIF, and CCL2 that support tumor cell proliferation and IL-6, C3, ANXA-1, and VEGFa that modulate immune cell compartment, particularly myeloid cells." (PMID 38213954, 2023). "It works by blocking the function of the vascular endothelial growth factor A (VEGF-A) and the growth of blood vessels that are needed to support tumor growth." (PMID 37894789, 2023).
tumor (continued). "Herein, we reported, for the first time, that ESM1 activates the downstream MAPK pathway by binding to the membrane receptor c-Met on the surface of HUVEC cells to promote the production of HIF1α, VEGFA, and MMP9, eventually promoting tumor angiogenesis." (PMID 38201620, 2023). "We also observed that tumor and endothelial cells released vascular endothelial growth factors, including VEGFC and VEGFA, as well as platelet-derived growth factors, including PDGFA and PDGFC." (PMID 37333982, 2023). "The ensuing release of trophic factors, metabolic regulators, and immunosuppressive molecules by M2-like macrophages, including vascular endothelial growth factor A (VEGFA), PGE2, IL-6, IL-10, among others, ultimately accelerates tumor progression." (PMID 37968714, 2023). "The effect of phycocyanin in metastasis was demonstrated through downregulation of vascular endothelial growth factor A (VEGF-A), MMP-2, and MMP-9, which are required for tumor invasion and metastasis." (PMID 37111349, 2023). "However, anti-VEGFA therapy is a direct reduction in the rate of tumour growth rather than an induction of tumour regression, and some drugs slow tumour growth without necessarily causing tumour shrinkage." (PMID 37389120, 2023). "This led to suppression of hypoxia-inducible factor 1 α (HIF-1α) activation, reduced production of vascular endothelial growth factor A (VEGF-A), and decreased growth of tumor blood vessels." (PMID 37111542, 2023). "For example, a group of VEGFA+ TAMs highly expressed hypoxia-inducible genes such as SLCA2, HK2, ANGPTL4, and VEGFA, which is beneficial for tumor angiogenesis." (PMID 37187731, 2023). "Specifically, STAT4 overexpression was correlated with an increased abundance of CAFs within the tumor microenvironment that was further accompanied by increased concentrations of CAF-secreted factors IL6, CXCL12, and VEGFA." (PMID 37173951, 2023). "Intraperitoneal AgNPs treatment beginning on the day of tumor inoculation enhanced mice survival, reduced the proliferation of ascitic EAC cells, and suppressed the activity of HIF1α, TNF-α and VEGFa genes." (PMID 37111584, 2023). "The selected targets were patient-specific, as the analysis of another individual’s HPV+ OPSCC, showed that although some interactions, such as VEGFA/NRP1 and VEGFA/GPC1 were present, the most active L-Rs in the tumor were VEGFA/NRP2 and EGFR-related pathways." (PMID 37704757, 2023). "It has been revealed that miR-138-5p functions as a tumor suppressor in HCC and suppresses VM by binding to the 3′UTR of HIF-1α mRNA and further downregulating the expression of HIF-1α and VEGFA." (PMID 37274242, 2023). "A relevant feature was the overexpression of factors such as VEGFA, VEGFC and Ang2, which are not only pro-angiogenic, but also support the growth of tumor cells." (PMID 36874116, 2023). "Immunohistochemical analyses of tumor sections from patients with KRAS-mutant NSCLC showed correlations between BACH1 and VEGFA and BACH1 and VEGFR2." (PMID 37651203, 2023). "Furthermore, while Mint3 depletion sensitized cancer cells to chemotherapy via HSP70 reduction, other mechanisms such as reduced VEGFA production and physical characteristics such as reduced tumor size may further contribute to the enhanced efficacy of chemotherapy in Mint3-depleted tumors." (PMID 38081808, 2023). "Several classical signaling pathways, such as IL-6/signal transducer and activator of transcription (STAT3), HIF1/VEGFA, and PI3K/AKT, have been shown to regulate tumor angiogenesis." (PMID 36720310, 2023).